BORCS6 (BLOC-1 related complex subunit 6)
Description:
As part of the BORC complex may play a role in lysosomes movement and localization at the cell periphery. Associated with the cytosolic face of lysosomes, the BORC complex may recruit ARL8B and couple lysosomes to microtubule plus-end-directed kinesin motor.
Synonyms: C17orf59; FLJ20014; PRO2472
Tractability: No criterion of Open Targets' tractability assessment is met for any kind of drug.
Gene: Protein-coding gene on chromosome 17 (8,188,345 to 8,190,180, reverse strand). Ensembl gene ENSG00000196544.
Subcellular location: Lysosome membrane
Subcellular location (Human Protein Atlas): Golgi apparatus; Vesicles
Gene Ontology:
Molecular function: identical protein binding; protein binding
Biological process: lysosome localization; organelle transport along microtubule; regulation of endosome size; regulation of lysosome size
Cellular component: BORC complex; cytoplasmic side of lysosomal membrane; lysosomal membrane
Genetic constraint (gnomAD): Loss-of-function variants: 10 observed, 9.78 expected, observed/expected ratio (o/e) 1.02, 90% interval 0.63 to 1.68. That is too few expected variants to judge how well the gene tolerates losing a copy. Missense variants: 389 observed, 343.96 expected, observed/expected ratio (o/e) 1.13, 90% interval 1.04 to 1.23. Synonymous variants: 206 observed, 163.01 expected, observed/expected ratio (o/e) 1.26, 90% interval 1.13 to 1.42.
Homologues: Orthologues: chimpanzee BORCS6 (99% identical), macaque BORCS6 (96% identical), pig BORCS6 (83% identical), dog BORCS6 (77% identical), mouse Borcs6 (74% identical), rat Borcs6 (73% identical), zebrafish borcs6 (36% identical), tropical clawed frog borcs6 (21% identical), Drosophila melanogaster BORCS6 (20% identical), Caenorhabditis elegans blos-7 (13% identical).